BRCA2 (BRCA2 DNA repair associated)
Diseases named in the same sentence as BRCA2 in open-access papers (continued):
Sharing a sentence is not in itself a finding about the gene and the disease.
breast cancer (continued). "This is consistent with previous findings in both human breast cancer and canine MGTs regarding the risk associated with BRCA2 mutations." (PMID 41168812, 2025). "According to the National Comprehensive Cancer Network, more than 60% of women with a pathogenic germline mutation in BRCA1 or BRCA2 are projected to develop breast cancer over the course of their lifetime." (PMID 41002733, 2025). "A randomized, double-blind, phase III clinical trial (NCT02849496) demonstrated that adding olaparib to neoadjuvant or adjuvant chemotherapy significantly improved IDFS in patients with early-stage HER2- breast cancer who also had a BRCA1 or BRCA2 mutation." (PMID 40134916, 2025). "A case–control study included 1665 pairs of women with BRCA1 (n = 1243 pairs) and BRCA2 P/LP variants (n = 422 pairs) to assess the association between breastfeeding and breast cancer risk." (PMID 39858629, 2025). "In fact, BRCA1 and/or BRCA2 mutations account for 5 to 10% of all breast cancers and 20 to 25% of hereditary breast cancers." (PMID 40507272, 2025). "Carriers of BRCA1 germline pathogenic variants have a significantly high lifetime risk of breast cancer – up to 72%, whereas BRCA2 carriers have a slightly lower but still a substantial risk of around 69%." (PMID 40390061, 2025). "Research into the BRCA2 gene locus and its association with mammary tumors has led to the identification of specific mutations within canine BRCA2." (PMID 41227463, 2025). "Men carrying BRCA2 mutations have a significantly increased risk of developing breast cancer compared to the general male population." (PMID 40243654, 2025). "Patients treated for serous ovarian cancer with mutations in the BRCA1 or BRCA2 genes are at high risk of breast cancer and should be screened with mammography and breast MRI." (PMID 40406472, 2025). "In summary, in the Colombian population, there is a great diversity of germline mutations in genes other than BRCA1 and BRCA2 that are associated with breast cancer." (PMID 40259910, 2025). "In contrast, HER2-negative breast cancer (BC) patients showed a numerically higher rate of pCR in BRCA1 vs. BRCA2 mutation carriers [38/69 (55%) vs. 13/36 (36%), P = 0.1]." (PMID 40547808, 2025). "Inherited mutations in the tumor-suppressor genes like BRCA1 and BRCA2 confer a hereditary predisposition to breast cancer." (PMID 40904409, 2025). "Although PVs have been reported across all exons of the BRCA1 and BRCA2 genes, variation hotspots highly associated with the development of breast cancer have been identified." (PMID 40071159, 2025). "Recruiting enough BRCA1 and BRCA2 mutation carriers for statistically significant findings is difficult, as they represent only a small subset of breast cancer patients." (PMID 40296163, 2025). "In this study, we investigated the Met1915Thr polymorphism of the BRCA2 gene among breast cancer patients in our population." (PMID 40843725, 2025). "Age appears to be an important modifier in the association between the BRCA2 Met1915Thr polymorphism and breast cancer risk." (PMID 40843725, 2025). "Olaparib, the first FDA-approved PARP inhibitor, has been approved as an adjuvant treatment option for HR+/HER2- ABC with germline BRCA1 or BRCA2 mutations or early-stage, high-risk breast cancer that has received neoadjuvant or adjuvant chemotherapy." (PMID 40134916, 2025). "Women with germline pathogenic variants in BRCA1 or BRCA2 (BRCA1/2 carriers) have about a 70% lifetime risk of developing breast cancer (BC)." (PMID 40728683, 2025). "This study was conducted to analyze the association between genetic polymorphisms of breast cancer genes 1 (BRCA1) and 2 (BRCA2), which are well known for their association with breast cancer and the development of thyroid cancer." (PMID 40361383, 2025).
breast cancer (continued). "Most guidelines on breast cancer surveillance for BRCA1 and BRCA2 P/LP variant carriers recommend starting breast screening at 25 years or individualizing the screening according to family history if a breast cancer diagnosis before age 30 is present." (PMID 39858629, 2025). "Here, we report a metastatic breast cancer case where a germline BRCA2 mutation was identified via tissue-based gene panel testing, necessitated by prior bone marrow transplantation precluding standard blood-based BRCA1/2 testing." (PMID 40065879, 2025). "The nomogram enables the prediction of the possible 5- or 10-year cumulative risk of CBC for BRCA1 and BRCA2 P/LP variant carriers after their first breast cancer diagnosis." (PMID 39858629, 2025). "Pathogenic variants in BRCA1 and BRCA2 are associated with an increased risk of developing several types of cancer, including breast cancer." (PMID 40296163, 2025). "Despite studies suggesting a role for the BRCA2 Met1915Thr polymorphism in breast cancer risk, a considerable number of investigations have failed to confirm a consistent association." (PMID 40843725, 2025). "This case study details a 57-year-old woman with heavily pretreated, hormone receptor-positive (HR+), HER2-negative advanced breast cancer harboring a pathogenic germline BRCA2 mutation." (PMID 41142243, 2025). "BRCA1 and BRCA2 mutations, known risk factors for breast cancer globally, are also present among Arab women, though specific mutations and their frequencies can vary significantly." (PMID 41294844, 2025). "A prospective cohort analysis evaluated the association between chemoprevention and the risk of breast cancer in unaffected women with BRCA1 or BRCA2 P/LP variants." (PMID 39858629, 2025). "All of our BARD1 mutation carriers developed high-grade breast cancer, while only 44.7% of BRCA2 mutation carriers (p-value = 0.004) and 39.7% of mutation-negative patients (p-value < 0.001) developed high-grade breast cancer." (PMID 40805222, 2025). "Genetic factors contribute to 5% to 10% of cases, and women with BRCA1 or BRCA2 mutations face a 50% to 85% lifetime risk of developing breast cancer." (PMID 39960903, 2025). "Metachronous pancreatic ductal adenocarcinoma (PDAC) following breast cancer is rare and often linked to pathogenic variants in high-penetrance genes such as BRCA2." (PMID 41229501, 2025). "The follow-up of patients with BRCA1 and BRCA2 mutations should be longer due to the risk of breast cancer." (PMID 40406472, 2025). "This procedure reduces the risk by up to 95% in women with germline mutations in the BRCA1 or BRCA2 genes and by up to 90% in women with a strong family history of breast cancer." (PMID 40243654, 2025). "The aim of this study was to determine the distribution of the BRCA2 Met1915Thr polymorphism (rs4987117) in the Azerbaijani population and to evaluate its potential association with breast cancer risk." (PMID 40843725, 2025). "The monogenic variant analysis identified 21 loss-of-function (LOF) variants in the cohort, but only one (BRCA2 9976A > T) was common among breast cancer cases." (PMID 41386870, 2025). "While men generally have a low risk of developing breast cancer, BRCA2 mutations raise that risk substantially, and they also increase the likelihood of developing prostate cancer, potentially at a younger age and with more aggressive forms." (PMID 41011057, 2025). "Around 10–15% of breast cancer cases in young women are diagnosed in patients with germline pathogenic or likely pathogenic variants in the BRCA1 or BRCA2 genes." (PMID 41077566, 2025). "Individuals with pathogenic variants in the BRCA1 and/or BRCA2 genes face elevated risks of cancer, including a 70% lifetime risk of breast cancer and 40% lifetime risk of ovarian cancer." (PMID 40862808, 2025).
breast cancer (continued). "Herein, we present a case of advanced ICC with a breast cancer susceptibility gene-2 (BRCA2) mutation, treated with preoperative chemotherapy, including cisplatin, followed by surgery, in which we achieved a pathologic complete response." (PMID 39974545, 2025). "Background/Objectives: Genetic polymorphisms in the BRCA2 gene have been implicated in breast cancer susceptibility." (PMID 40843725, 2025). "Women who have inherited germline mutations in BRCA1 or BRCA2 are at a significantly elevated lifetime risk of developing breast cancer, estimated at 80% and 72%, respectively." (PMID 39863726, 2025). "HRD gained prominence with the discovery that mutations in the breast cancer genes BRCA1 (Breast Cancer Gene 1) or BRCA2 (Breast Cancer Gene 2) impair HRR." (PMID 40864792, 2025). "In population-based studies, BRCA1 and BRCA2 P/LP variants were associated with a significantly increased risk of breast cancer, with an odds ratio (OR) ranging from 7.62 to 10.57 and 5.23 to 5.85, respectively." (PMID 39858629, 2025). "Mutations in BRCA1 and BRCA2 account for the majority of hereditary breast cancer cases and approximately 5 – 10% of all cases." (PMID 40800071, 2025). "Specifically, BRCA1 mutations are strongly associated with basal-like breast cancers, while BRCA2 mutations are more frequently linked to luminal-like breast cancer." (PMID 40867511, 2025). "Despite only 5% to 10% of breast cancer cases being inherited, approximately 55% to 65% of individuals with a BRCA1 gene mutation and 45% of those with a BRCA2 gene mutation develop breast cancer by the age of 70." (PMID 40427149, 2025). "For example, researchers suggested that the canine BRCA2 gene locus is associated with mammary tumors." (PMID 41227463, 2025). "Another study further confirmed a statistically significant association between the BRCA2 Met1915Thr variant (rs4987117) and increased breast cancer risk." (PMID 40843725, 2025). "A study from Saudi Arabia additionally highlighted significant germline mutations in the BRCA1 and BRCA2 genes in high-risk breast cancer patients, essential for understanding breast cancer susceptibility in Arab women." (PMID 41294844, 2025). "Genetic predisposition, particularly mutations in Breast Cancer type 1 susceptibility protein (BRCA1)/Breast Cancer type 2 susceptibility protein (BRCA2), significantly increases breast cancer risk (Pal, Das & Pandey, 2024)." (PMID 40034665, 2025). "Women with pathogenic BRCA1 or BRCA2 variants have many options to reduce their known high risk of developing breast cancer." (PMID 40599862, 2025). "What is the prevalence of BRCA1 and BRCA2 pathogenic or likely (P/LP) variants in an unselected population of women with breast cancer?" (PMID 40952741, 2025). "Some researchers developed gene-specific predictors for BRCA1 and BRCA2, showing their superiority over genome-wide predictors in evaluating breast cancer-associated variants." (PMID 41263939, 2025). "One BRCA2 mutation observed only in the Chinese ethnicity of the Brunei breast cancer population suggest a probability of the mutation being a founder effect in the Southern Chinese population." (PMID 40531958, 2025). "Genomic instability in tumors is significantly increased due to endogenous and exogenous factors, such as breast cancer 1/breast cancer 2 (BRCA1/BRCA2) gene mutations and oxidative stress." (PMID 40444043, 2025). "Mutations within exon 11 of BRCA2 have been linked to a higher risk of ovarian cancer than of breast cancer." (PMID 40427158, 2025). "While BRCA1 and BRCA2, which occur in approximately 1/400 individuals, are well-known genes contributing to a high risk of breast cancer, CS which occurs in 1/200,000 is less well known." (PMID 41180948, 2025). "Individuals carrying BRCA1 pathogenetic variant genes have a cumulative risk of developing breast cancer of 72% (95% confidence interval [CI] = 65% to 79%) and 69% in case of BRCA2 genes (95% CI = 61% to 77%)." (PMID 41092066, 2025).
breast cancer (continued). "Bilateral risk-reducing salpingo-oophorectomy (BRRSO) is even more invasive, and it can be used to decrease the risk in BRCA2 carriers, as they can potentially develop breast cancers and ovarian neoplasms with a higher risk." (PMID 41303129, 2025). "Women with a history of breast cancer who are found to carry a BRCA1 or BRCA2 mutation are eligible for insurance coverage for RRM and RRSO." (PMID 41083355, 2025). "Patients with a pathogenic germline variant in BRCA2 also have an increased risk of developing breast cancer." (PMID 39639158, 2025). "BRCA1 and BRCA2 germline mutation carriers had an increased cumulative risk of 72% and 69%, respectively to develop breast cancer by 80 years old." (PMID 40531958, 2025). "In conclusion, our findings suggest a modest but statistically significant association between the BRCA2 Met1915Thr polymorphism and an increased risk of breast cancer." (PMID 40843725, 2025). "Chemotherapy receipt was 80.6% in BRCA1-associated breast cancers compared to 56.9% in BRCA2 and 84.2% in PALB2 associated breast cancers (p < 0.001)." (PMID 40275390, 2025). "Carriers of pathogenic BRCA1 variants exhibit an estimated cumulative breast cancer risk of approximately 72% by the age of 80, while individuals harboring BRCA2 mutations demonstrate a comparable lifetime risk of around 69%." (PMID 40904409, 2025). "BRCA1 and BRCA2 (BRCA1/2) mutation screening is recommended for patients with advanced breast cancer or early breast cancer suspected to have hereditary origins based on family history or tumor characteristics." (PMID 40065879, 2025). "Germline pathogenic and likely pathogenic variants in the BRCA1 and BRCA2 genes (BRCApv) account for 3–5% of breast cancer (BC) incidence and are linked to hereditary breast and ovarian cancer syndrome." (PMID 40408052, 2025). "Conversely, in the BRCA2 P/LP variant group, three of the eleven women who developed breast cancer were on tamoxifen, compared to eight in the placebo group (RR 0.38; 95% CI 0.06–1.56)." (PMID 39858629, 2025). "Cancer cells defective in HR (e.g. BRCA2 deficient breast cancer) are hypersensitive to PARP inhibitors such as Olaparib." (PMID 39975112, 2025). "Of 100 patients, 20% were positive for BRCA1 and 11% for BRCA2 (BRCA: breast cancer susceptibility gene)." (PMID 41020087, 2025). "The usefulness of prophylactic surgery and surveillance for hereditary breast cancer in breast cancer patients with germline BRCA1 or BRCA2 variants has been demonstrated." (PMID 39831988, 2025). "Approximately 12% of breast cancers in the Ashkenazi Jewish population are attributable to mutations in the BRCA1 or BRCA2 gene." (PMID 39941369, 2025). "Mutations in BRCA2 are associated with an increased risk of developing breast cancer and other oncological diseases." (PMID 40843725, 2025). "The present study is based on an adherent analysis of the literature focused on genes deregulated by BRCA1 and BRCA2 mutations in breast cancer and modulated by treatments." (PMID 40136510, 2025). "Bilateral mastectomy, particularly in patients with BRCA1 or BRCA2 mutations, has been shown to increase overall survival and reduce breast cancer risk by over 85%." (PMID 40806826, 2025). "Mutations in BRCA1 and BRCA2 account for roughly 20–50% of hereditary breast-cancer cases and significantly increase women’s lifetime risk of both breast and ovarian carcinomas." (PMID 40843725, 2025). "A pathogenic germline mutation associated with increased breast cancer risk was identified in 21% of patients, most commonly BRCA2 (11%)." (PMID 41156045, 2025). "Pathogenic germline variants in the breast cancer susceptibility gene, BRCA2, are commonly known for an increased risk of breast and/or ovarian cancer." (PMID 40072281, 2025). "The ASCO/ASTRO/SSO guidelines recommend offering CRRM for women with breast cancer carrying a BRCA1 or BRCA2 P/LP variant and who have been treated or are being treated with unilateral mastectomy." (PMID 39858629, 2025).
breast cancer (continued). "The percentage of breast cancer patients that are positive for BRCA1 or BRCA2 mutations varies depending on strategy utilized and the population tested." (PMID 41568010, 2025). "Concerns regarding ipsilateral breast tumor recurrence (IBTR) and regional recurrence in patients with breast cancer with BRCA1 or BRCA2 pathogenic variants undergoing BCT still persist." (PMID 40366658, 2025). "Women with a BRCA1 mutation face a significantly increased lifetime risk of breast cancer, with estimates ranging from 60% to 72%, while those with a BRCA2 mutation have a high lifetime risk of 55% to 77%." (PMID 40941615, 2025). "This cohort study examines the prevalence of pathogenic or likely pathogenic variants in BRCA1 and BRCA2 in women with breast cancer in a racially and ethnically diverse population." (PMID 40952741, 2025). "A Chinese study from FUSCC revealed HER2 positivity in 7.3% of BRCA1 germline mutations and 8.7% of BRCA2 germline mutations in breast cancer." (PMID 39985003, 2025). "The review identified several significant risk factors for MBC, including BRCA2 mutations, hormonal imbalances (particularly estrogen and testosterone levels), and family history of breast cancer." (PMID 40486874, 2025). "It acts against cancers in people with hereditary BRCA1 or BRCA2 mutations including breast cancer and some ovarian and prostate cancers." (PMID 40303990, 2025). "Toxicities limit combination of PARP inhibitors (PARPi) and chemotherapy in patients with germline BRCA1 and BRCA2 pathogenic variant (gBRCAm) breast cancer." (PMID 40360463, 2025). "A prospective study evaluated the association between annual MRI surveillance and the risk of breast cancer mortality among women carrying BRCA1 or BRCA2 P/LP variants." (PMID 39858629, 2025). "The biologic differences between BRCA1 and BRCA2-associated breast cancers have been well established in the literature, with data on PALB2 continuing to evolve." (PMID 40275390, 2025). "Ovarian cancer is a lifetime risk of 40%–60% for women who carry hereditary BRCA1 (Breast Cancer gene 1) and BRCA2 (Breast Cancer gene 2) mutations." (PMID 41164269, 2025). "Out of the 11 patients with concordant P/LPGVs in BRCA2, 3 had variants identified in ovarian cancer, 4 in breast cancer, and 1 each in brain, uterine, pancreatic, and upper GI malignancies." (PMID 41465149, 2025). "For example, the estimated absolute lifetime risk of breast cancer associated with PALB2 variants is about 40%: a high frequency that approaches the risk of breast cancer in individuals with BRCA2 variants." (PMID 39831988, 2025). "BRCA1 mutation carriers have a lifetime risk of approximately 60-70% for developing breast cancer, while those with BRCA2 mutations have a risk of around 45-55%." (PMID 40599862, 2025). "Breast cancer-specific studies have shown that general pathogenicity predictors underestimate the relevance of BRCA1/BRCA2-associated variants, leading to inconsistent classification outcomes." (PMID 41263939, 2025). "In our study, we observed that the rs80359550 polymorphism in BRCA2 was strongly associated with breast cancer risk in the western population of Iran." (PMID 40158114, 2025). "Germline mutations in the BRCA1 and BRCA2 genes are well-established risk factors for distinct subtypes of breast cancer." (PMID 40867511, 2025). "BRCA1- and BRCA2-associated hereditary breast and ovarian cancers are characterized by an increased risk of developing breast cancer in both men and women, as well as ovarian, fallopian tube, and primary peritoneal cancers." (PMID 40427158, 2025).